IL33 (interleukin 33)
Diseases named in the same sentence as IL33 in open-access papers (continued):
Sharing a sentence is not in itself a finding about the gene and the disease.
allergic disease (continued). "IL-33 also acts on mast cells, central mediators of allergic diseases, by enhancing their degranulation and cytokine production, subsequently contributing to inflammation and tissue remodelling." (PMID 41284319, 2025). "Interleukin-33 (IL-33) is a cytokine that plays an important role in inflammatory and allergic diseases, including AD." (PMID 41155460, 2025). "IL1RL1 (ST2) encodes the IL-33 receptor, and the IL-33/ST2 axis is a well-established driver of type 2 immune responses and allergic diseases, including AC." (PMID 41476961, 2025). "Interleukin-33 (IL-33), a member of the IL-1 cytokine family and an alarmin released upon cellular stress, is crucially involved in type 2 immunity, allergy, and inflammation." (PMID 40659660, 2025). "IL-33 is a tissue-derived nuclear cytokine that promotes type 2 immune responses during allergy and helminthic infection." (PMID 40069907, 2025). "We have summarised the role of basophils and type 2 epithelial cytokines, specifically TSLP and IL‐33, in allergic diseases and helminth infections in humans and mice." (PMID 39654685, 2024). "TSLP and IL-33 are two alarmin cytokines that drive type 2 responses at the skin barrier level and hence play a role in the early development of allergic reactions." (PMID 39076967, 2024). "As such, IL-33 can activate mast cells and eosinophils during type 2 immune responses in allergic diseases." (PMID 38541674, 2024). "Increased IL-33 activity affects the onset and severity of allergic diseases; however, ILC2 has anti-inflammatory effects and protects against atherosclerosis." (PMID 38674885, 2024). "IL-33 has a well-known impact on immune cells, especially Th2 cells in allergic disease and parasitic infections." (PMID 38662248, 2024). "Collectively, since basophils have unique pathological roles in IL‐33‐contributed allergic diseases, it would be worth targeting both basophils and mast cells in potential therapies for IL‐33‐contributed allergic diseases." (PMID 39654685, 2024). "The studies summarised in this review indicate that type 2 epithelial cytokines of TSLP and IL‐33 play a role as positive modulators in activation of basophils both directly and also indirectly, leading to exacerbation of allergic reactions." (PMID 39654685, 2024). "During the search for compounds from natural sources with potential as therapeutic agents for allergic diseases via IL-33 signal modulation, we discovered significant IL-33 inhibitory activity in the methanol extract of Canavalia gladiata (sword bean) pods." (PMID 39061836, 2024). "IL-33, a cytokine that is known to be involved in allergic diseases, plays diverse roles in the tumor immune system." (PMID 38825642, 2024). "IL-33 plays a significant role in inflammation, allergy, and host defence against parasitic helminths." (PMID 38890291, 2024). "Central to this intricate network is the cytokine IL-33, which has gained significant attention for its critical role in various diseases, from allergy to cancer, triggering type 2 immune responses, among others." (PMID 39149516, 2024). "IL-33 plays a pro-inflammatory role in allergic diseases and is recognized as an important contributor to Th2-type immune responses." (PMID 38288067, 2023). "In the present study, we first revealed evidence of IL-33 in prenatal DEHP exposure-related childhood allergies." (PMID 37545493, 2023). "Resveratrol has been shown to target the MK2/3-PI3K/Akt axis in allergic diseases, inhibiting IL-33-mediated mast cell activation and therefore alleviating symptoms." (PMID 37686309, 2023). "Overall, IL-33 has a wide range of roles in the gut, including immunological modulation, allergy reactions, immune homeostasis, tumor immunity, and intestinal barrier fortification." (PMID 37686309, 2023). "The biological effect of IL-25 and IL-33 in driving type-2 immune response was extensively demonstrated in the allergy and helminth infection model." (PMID 37337050, 2023).
allergic disease (continued). "Genome-wide association studies (GWAS) have shown an association between allergic diseases and genetic polymorphisms in genes such as TSLP, IL33, and IL1RL1, which encode the IL-33 receptor ST2." (PMID 36941691, 2023). "Interleukin 33, an integral cytokine of the IL-1 family, has emerged as a key player in the pathophysiology of various inflammatory and allergic diseases, as well as certain cancers." (PMID 37762328, 2023). "As one of the reported TLR signaling suppressors, ST2L (a transmembrane receptor for IL-33) shows high levels on diverse hematopoiesis-derived cells under allergy conditions." (PMID 36834541, 2023). "The epithelial cell–derived danger signal mediators IL-33, TSLP, and IL-25 are consistently associated with type 2 immune responses in allergic diseases." (PMID 36941691, 2023). "An essential cytokine of the T helper 2 (Th2) immune response that predominates in allergic diseases, such as allergic rhinitis, is interleukin-33 (IL-33)." (PMID 36644088, 2022). "Several neutralizing antibodies against IL-33 have been developed, which have been used in clinical trials for the treatment of allergic diseases." (PMID 35958837, 2022). "Type II innate lymphoid cells, which participate in allergic disease maintenance, are regulated by IL-33, among other cytokines." (PMID 35237264, 2022). "Previous studies have demonstrated that blocking the interaction of IL-33/ST2 alleviates the severity of allergic disease by reducing Th2 cytokine production, eosinophilic inflammation, serum IgE level, and airway hyper­reactivity." (PMID 36644088, 2022). "Together, these data demonstrate that HSP90 in MCs is essential for mediating IL-33-driven allergic reactions." (PMID 36142767, 2022). "The cytokines TSLP and IL-33 signaling pathways are essential in various inflammatory and allergy reactions." (PMID 36160850, 2022). "In a prior study, CD34+ stem cells from blood donors express ST2L and produce IL-5 and IL-13 in response to IL-33 supporting these stem cells as potential effector cells in allergic diseases." (PMID 36177009, 2022). "Blocking the IL33/ST2 axis is protective in allergic diseases, especially in the respiratory system." (PMID 35958837, 2022). "Interleukin-33 is a cytokine, classically known for the proinflammatory role it plays in allergic disease." (PMID 34531552, 2022). "In line with that, in animal models, HSPs and IL-33-activated MCs were identified as import for the development of allergic reactions such as contact hypersensitivity (CHS)." (PMID 36142767, 2022). "VD also seems to have a role in allergic diseases and bone pathologies mediated by Th2 cells, via the IL-31/IL-33 axis, which is another new area to investigate the intricate overlapping mechanisms that connect allergies and osteoporosis." (PMID 36009422, 2022). "IL-33 is a member of the IL-1 superfamily of inflammatory cytokines and has been shown to be important and elevated in allergic diseases such as EoE, asthma and atopic dermatitis." (PMID 36177009, 2022). "IL-33 is a dangerous signal mediator of epithelial cells and is associated with the response of TH2 lymphocytes in allergic diseases, promoting the activation of innate lymphoid cells 2 (ILC2) and involving innate inflammation." (PMID 36362030, 2022). "IL‐33 is involved in allergic diseases such as asthma, anaphylaxis, atopic dermatitis and allergic rhinitis." (PMID 35344301, 2022). "ST2, the receptor of IL-33, is also a key component in promoting Th2 responses and triggering eosinophilic inflammation in allergic diseases." (PMID 35633657, 2022). "In our study, we examined the antiallergic activity of Brazilian green propolis (BGP) and isolated the active compound that can suppress an allergy-sensitive gene, IL-33, expression and eosinophilia." (PMID 36080225, 2022). "Next, we examined the effect of trifuhalol A on the expression of IL-33, which is related to pseudoallergic or allergic reactions." (PMID 36077570, 2022).
allergic disease (continued). "Recent studies have suggested that IL-33 is mainly involved in the development of allergic diseases." (PMID 34576749, 2021). "Connecting all these facts with our data presented here, we suggest that the principle of ATP/IL‐33‐hyperactivated MCs is relevant for the development of cytokine storm syndromes, shock symptoms or allergic reactions." (PMID 34142370, 2021). "Our results demonstrate that short and dysfunctional telomeres hamper HDM‐induced allergy by reducing the expression of IL33, which is highly produced by bronchial Club cells and reported to regulate EMT and collagen deposition." (PMID 33942458, 2021). "Previous studies confirmed IL-33 played a crucial part in immune regulation of various diseases including autoimmune diseases, allergic diseases, and organ transplantation." (PMID 34950738, 2021). "Pro-inflammatory cytokines (e.g., IL-12, IL-25 and IL-13) play an important role in driving allergic conditions including allergic asthma; IL-33, IL-4 and IL-5 are key factors that drive allergy." (PMID 34638811, 2021). "Interleukin-33 (IL-33), a member of the IL-1 cytokine family, plays a critical role in maintaining tissue homeostasis as well as pathological conditions, such as allergy, infectious disease, and cancer, by promoting type 1 and 2 immune responses." (PMID 34209038, 2021). "For example, fungi, mites and some fruits have antigenic activity; they also induce IL-33-dependent allergies through cysteine protease activity." (PMID 34498700, 2021). "Recently, it has been shown that IL-33 is involved in the pathogenesis of several inflammatory diseases, including allergic diseases, infectious diseases, and neuropathic pain." (PMID 35095557, 2021). "TSLP, IL-33, and IL-25 secreted from HNECs were known as “master switches” in the development of allergic diseases." (PMID 34899052, 2021). "The efficacy of anti-TSLP, anti-IL-33 and anti-IL-25 as monotherapies for treatment of allergic diseases was addressed in a number of studies." (PMID 34084159, 2021). "Because previous studies have identified TSLP, IL-25 and IL-33 as potent activators of innate lymphoid cells in allergic and non-allergic disease states, we chose to assess potential activation of lung ILC2 by these epithelium-derived cytokines." (PMID 34266437, 2021). "Several studies have explored the roles of IL-33 in allergic diseases and found high expressions of IL-33 in the skin or airway epithelial cells in AD or airway inflammation." (PMID 32973790, 2020). "Through ST2 binding, IL-33 is known to be able to induce helper T cells, mast cells and eosinophils to produce type 2 cytokines in allergy." (PMID 32286393, 2020). "In this regard, it is well recognised that the IL‐33/ILC2 axis plays a critical role in allergic disease." (PMID 32566227, 2020). "The two Th2 cytokines IL-31 and IL-33 demonstrated to be relevant in the pathogenesis of both allergy and osteoporosis as well as autophagy and these too have been suggested as potential therapeutic target." (PMID 31973226, 2020). "This expression profile of Th2 cytokines includes IL‐4, IL‐5, IL‐9 and IL‐13, suggesting the pathogenesis of IL‐33‐induced neutrophils in airway allergic disease." (PMID 32566227, 2020). "Interleukin-33 (IL-33), is a member o the IL-1 family that is involved in the Th2 mediated immune response, host defences and allergic diseases." (PMID 32280308, 2020). "Many studies of the ILC2 potent alarmin IL-33 in allergic diseases have focused on barrier tissues such as the lung, but our findings suggest that IL-33 has additional roles in the bone marrow." (PMID 32582171, 2020). "In a model of papain-induced allergy, MC stimulated with IL-33 have been shown to be crucial to suppress papain-induced inflammation by promoting regulatory T cells." (PMID 32286393, 2020).
allergic disease (continued). "Secreted IL-1α alarmin targets epithelial cells in an autocrine manner, to release GM-CSF and IL-33 which recruits dendritic cells, and neutralization of these triad cytokines dampens allergy development." (PMID 33424827, 2020). "IL-25 and IL-33 are epithelial cell-derived cytokines that lead to Th2 cytokine-mediated allergy responses, either directly by the Th2 cell or indirectly via dendritic cell activation." (PMID 32824648, 2020). "Many studies have also indicated IL-33 as an important factor in the pathogenesis of multiple inflammatory, autoimmune and allergic diseases, such as SLE, rheumatoid arthritis (RA), and inflammatory bowel disease (IBD)." (PMID 32679721, 2020). "IL-33 has long been studied in the context of Th2-related immunopathologies, such as allergic diseases and parasitic infections." (PMID 33329534, 2020). "Recently, IL-33 was found to induce the Th2 inflammatory response in allergic diseases, especially AD31." (PMID 32792500, 2020). "The expression of allergy genes (IL-13RA1, IL-33, FCERIG, CHIL1) was also enhanced in the OVA + PM group when compared to the OVA group indicating the possible exacerbation of AD." (PMID 32846909, 2020). "The dual importance of IL33 and MCs in allergies is well established, yet critical roles for the IL33-MC axis have also been uncovered in allergic, autoimmune, inflammatory disease as well as cancer and other diseases." (PMID 32719677, 2020). "IL-33 receptor activation is a potent inducer of type two immune responses which mediate the ejection of helminth parasites (as well as inducing allergic disease), and so the IL-33 pathway represents a central target for parasite immunomodulation." (PMID 32420871, 2020). "Studies in animal models that either administer or ablate IL‐33 support its contribution to the pathogenesis of allergic disease." (PMID 32566227, 2020). "Important findings include the identification of IL-33 and ST2 as major susceptibility loci in several genome-wide association studies of allergic diseases." (PMID 32582171, 2020). "An essential role of IL-33 in allergic diseases, such as bronchial asthma and atopic dermatitis, further highlights the immunomodulatory effects of IL-33 and thus also of weightlessness." (PMID 32423045, 2020). "In this review, we focus on the recent advances of the underlying intercellular and intracellular mechanisms by which IL-33 can regulate the allergic inflammation in various allergic diseases including allergic asthma and atopic dermatitis." (PMID 30886621, 2019). "Apart from the pathological role in allergic diseases, IL-33 participates in diverse immune regulatory events." (PMID 30886621, 2019). "Interleukin-33 (IL-33)/ST2–mediated mast cell activation plays important roles in the pathophysiology of allergic diseases." (PMID 31804564, 2019). "Initially, IL-33 was described for its role in promoting type 2 immunity in infectious and allergic diseases." (PMID 30949175, 2019). "Recent studies have suggested that the IL-33/ST2 interaction plays critical roles in the development of allergic diseases." (PMID 31804564, 2019). "IL-33, one of IL-1 gene superfamily members that plays dual functions in many inflamed diseases, such as cardiovascular diseases, allergy, multiple sclerosis (MS), stroke, and Alzheimer’s disease." (PMID 31291887, 2019). "Natural products and herbal medicines with the pluripotent activities to inhibit the production and actions of IL-33 are also promising candidates for further pharmacological evaluation for the treatment of allergic diseases." (PMID 30886621, 2019). "Recent studies suggest that the IL-33/ST2 interaction plays a critical role in the development of allergic diseases." (PMID 31804564, 2019). "Due to the likelihood of side effects with these allergic diseases, there is a paucity of research on the potential therapeutic role of IL-33 in humans." (PMID 31509992, 2019).
allergic disease (continued). "The future pharmacological strategy and application of traditional Chinese medicines targeting the IL-33/ST2 axis for anti-inflammatory therapy of allergic diseases were also discussed." (PMID 30886621, 2019). "Based on its acute effects on mast cells (and type 2 innate lymphoid cells), IL-33 is thought to play a critical role in the pathogenesis of allergic disease." (PMID 31804564, 2019). "The cell-autonomous circadian clock regulates IgE- and IL-33-mediated mast cell activation, both of which are key events in the development of allergic diseases." (PMID 31847374, 2019). "IL-33 has been considered as an emerging key factor in the development of allergic diseases, and its reduction can improve then by reducing pro-inflammatory cytokine production and Th2 type immune cell activation." (PMID 31316714, 2019). "Now in this study, we found that cGAMP functions as an allergy-prone adjuvant inducing strong type-2 immune responses to co-inhaled allergen in the airway which was dependent on IL-33 and its receptor ST2, which utilize MyD88-dependent signaling pathway." (PMID 31616416, 2019). "Numerous studies have demonstrated the particular importance of IL-33 in respiratory and allergic diseases." (PMID 30257479, 2018). "This indicates that dietary GOS facilitates budesonide treatment in its capacity to further decrease allergy driving mediators IL-33, CCL17 and CCL22, derived from both airway epithelial cells and DC." (PMID 30405619, 2018). "Experimental confirmation of rs4742170 functional significance for the IL33 transcriptional regulation would improve the understanding of IL-33 biology in the context of allergy." (PMID 30544846, 2018). "Recent data indicate that ILC2 cells producing large amounts of these cytokines in response to IL-33 play a prominent role in driving the systemic type-2 immune response and in the development of various allergic diseases." (PMID 30544846, 2018). "Recently, IL-33 has been considered as an emerging key factor in the development of allergic diseases." (PMID 29987222, 2018). "Although initially studied in the context of allergy, infection, and inflammation, over the past decade IL-33 has gained much attention in cancer immunology." (PMID 30483263, 2018). "IL-33 is an important mediator of allergy through its ability to induce Th2 cytokines and has been associated with development of severe AD25." (PMID 29416104, 2018). "IL-33 has been shown to be an important regulator of type-2 cytokine production and the pathogenesis of allergic diseases." (PMID 28721208, 2017). "Airway epithelial cell-derived thymic stromal lymphopoietin (TSLP) and IL-33 can enhance lung-resident group 2 innate lymphoid cells (ILC2s), and they play an important role in the development of allergic diseases." (PMID 28819104, 2017). "Relevant to allergy, IL-33 release was shown in response to the established adjuvant aluminum hydroxide (alum)." (PMID 28512632, 2017). "This shows that innate cytokines, such as TSLP, IL-25, and IL-33, are involved in the development of allergic disease by acting as a link between the innate and adaptive airways." (PMID 28912627, 2017). "HpARI binds to IL-33 (a critical inducer of allergy) and nuclear DNA, preventing the release of IL-33 from necrotic epithelial cells." (PMID 29045903, 2017). "IL-33 appears to function by activating ILC2s to produce large amounts of type-2 cytokines, and contributes to the occurrence and development of allergy." (PMID 27917896, 2016). "The roles of TSLP and IL33 in allergy were evaluated in TSLP receptor (TSLPR)- and IL33 receptor-deficient (T1/ST2) mice, respectively; TSLPR- and T1/ST2-knockout mice showed strong Th1 responses with high levels of IL2 and IFN-γ and impaired the Th2 response." (PMID 27826297, 2016). "Higher BPA levels result in increased TSLP, IL-33 and IgE from cord blood, which are biomarkers for allergies and asthma development later in life." (PMID 29051427, 2016).